LACTB (lactamase beta)
Diseases named in the same sentence as LACTB in open-access papers (continued):
Sharing a sentence is not in itself a finding about the gene and the disease.
tumor (28 papers, 2017 to 2025). "These mutations impair the tumor-suppressive function of wild-type LACTB and confer oncogenic-like properties to the protein." (PMID 39941048, 2025). "Previous studies on LACTB tumor suppression showed that LACTB OE caused a decrease in cell proliferation and tumor growth." (PMID 41223265, 2025). "This study shows that the M5L and R469K double mutations diminish the tumor suppressive effect of wild type LACTB and confer oncogene‐like function to LACTB protein." (PMID 39324579, 2024). "In general, our findings first show that the M5L and R469K double mutations diminish the tumor suppressive effect of wt‐LACTB and confer oncogene‐like function to LACTB protein." (PMID 39324579, 2024). "When the volume of subcutaneous tumour reached about 0.05–0.1 cm3, mice were treated with lenvatinib and intratumorally injected with adeno-associated virus expressing LACTB or sh-LACTB." (PMID 39047638, 2024). "In some tumors, LACTB exhibits low expression and functions as a tumor suppressor, which is associated with poor prognosis." (PMID 38149985, 2023). "The opposite results indicate that the M5L and R469K double mutations may diminish tumor suppressive role of wt‐LACTB and confer oncogene‐like function to LACTB." (PMID 39324579, 2024). "Importantly, LACTB is identified as a downstream target of lenvatinib, and adeno-associated virus-mediated overexpression and knockdown of LACTB notably enhance and attenuate the anti-tumour efficacy of lenvatinib in vivo, respectively." (PMID 39047638, 2024). "The role of LACTB in autophagy regulation further underscores its dual influence as both a tumor suppressor and, in certain contexts, an oncogene." (PMID 39941048, 2025). "Here, we identify serine beta-lactamase-like protein (LACTB), a filament-forming serine protease and tumor suppressor, as a regulator of IMM dynamics during apoptosis." (PMID 41223265, 2025). "The varied expression patterns of LACTB protein in different cancer types highlight its distinct functional roles in tumor biology." (PMID 39941048, 2025). "In HCC cells, OXCT1 was recently found to promote the succinylation of LACTB at K284, which inhibits its protein hydrolysis activity, thus promoting the proliferation of tumor cells and ultimately leading to the progression of HCC." (PMID 40867281, 2025). "In most cases, LACTB expression levels are inversely correlated with cancer cell proliferation but exhibit minimal impact on non-tumor cell growth." (PMID 39941048, 2025). "Collectively, these findings underscore the dual role of LACTB in cancer biology, as it can either promote cell cycle arrest to suppress tumor growth or, in certain contexts, support continuous cell cycle progression to support cancer development." (PMID 39941048, 2025). "The role of LACTB in regulating EMT in various cancers thus underscores its broader functional significance in tumor progression." (PMID 39941048, 2025). "In light of the differential regulation of LACTB in cancers, along with its unique tumor-suppressive or oncogenic functions, targeting LACTB represents an impending therapeutic strategy in precision medicine." (PMID 39941048, 2025). "Research on LACTB functions has shown that its enzymatic activity is essential for its tumor-suppressive role." (PMID 39941048, 2025). "Recent studies revealed a complex role for LACTB in regulating the cell cycle and influencing tumor growth in different cancers." (PMID 39941048, 2025). "Recent research identified LACTB as a critical regulator of cancer cell death pathways, predominantly acting as a tumor suppressor via mechanisms such as ferroptosis, autophagy, and apoptosis." (PMID 39941048, 2025).
tumor (continued). "β-lactamase-like protein (LACTB) is a β-lactamase-like protein located mainly in mitochondria and has been found to function as a tumor suppressor." (PMID 40867281, 2025). "LACTB (lactamase beta) is evolutionarily related to bacterial penicillin-binding/B-lactamase proteins, and its role in tumor biology remains controversial." (PMID 38254188, 2024). "The results showed that LACTB overexpression significantly retarded tumour growth, accompanied by the elevation of Fe2+, PTGS2, and 4HNE and the downregulation of GSH." (PMID 39047638, 2024). "The result showed that tumor volumes were markedly decreased in the LACTB knockdown group compared with those in the control group." (PMID 39324579, 2024). "HepG2 cells were thus replaced with SK-HEP-1 cells, the results showed that overexpression of LACTB led to a decrease in tumour volume and weight, whereas LACTB knockout exerted the opposite effects." (PMID 39047638, 2024). "Results from this study uncovered more detailed mechanistic functioning of LACTB tumour suppressive function, the knowledge of which can be beneficial for the design of more tuned cancer treatments." (PMID 36282364, 2023). "Increased expression of LACTB in these tumors results in the inhibition of tumor cell proliferation, migration, and invasion." (PMID 38149985, 2023). "One of the latest tumour suppressors, which was identified while researching tissues where cancer rarely occurs, is the serine beta-lactamase-like (LACTB) protein." (PMID 36282364, 2023). "The results showed that increased Slug levels indeed significantly counteracted the tumor suppressive ability of LACTB." (PMID 36375842, 2023). "Such an example can be found in a wide variety of tumour suppressors, one example being LACTB protein." (PMID 36282364, 2023). "LACTB was recently identified as a mitochondrial tumour suppressor that negatively affects cancer cell proliferation by inducing cell death and/or differentiation, depending on the cell type and tissue." (PMID 36282364, 2023). "We therefore decided to research in more detail the role of apoptosis, oxidative damage and cell survival in the mechanism of LACTB-mediated tumor suppression." (PMID 36282364, 2023). "LACTB is a recently discovered tumor-related gene that exhibits varying expression levels across different tumor types." (PMID 38149985, 2023). "LACTB is a newly discovered tumor-related gene that has emerged in recent years, distributed across various human tissues, and is localized in the mitochondrial intermembrane space." (PMID 38149985, 2023). "Similar results supporting a tumour suppressive effect of increased LACTB expression have been obtained for melanoma, gastric cancer, and lung cancer." (PMID 35626737, 2022). "Subsequently, the tumor-suppressive effects and prognostic values of LACTB were demonstrated in many different cancer types." (PMID 33507917, 2021). "The proportion of highly expressed LACTB in tumor tissues was significantly higher than that in normal tissues (P = 0.009), and this difference was also found in different sexes (P = 0.004)." (PMID 33507917, 2021). "Functionally, miR‐374a knockdown significantly inhibited proliferation and invasion of BRCA cells in vitro and tumor growth in vivo by upregulating LACTB expression." (PMID 29790671, 2018). "Stronger staining of LACTB and weaker Ki‐67 were observed in the tumor from the sh‐miR‐374a by IHC analysis." (PMID 29790671, 2018). "LACTB mRNA expression was frequently dysregulated in cancers, such as upregulation in tumor tissues of ESCA, STAD, and CESC, whereas downregulation in tumor tissues of LUAD, LIHC, and COAD, compared with normal tissues." (PMID 29790671, 2018). "Recent studies have revealed that LACTB was frequently repressed and functioned as a bona fide new tumor suppressor in a series of cancers, including BRCA." (PMID 29790671, 2018). "The current study reveals that LACTB exerts a tumor suppressor function by curbing mitochondrial phospholipid synthesis." (PMID 28642719, 2017).
tumor (continued). "In the context of expression of the HRASG12V or MYCT58A oncogenes, reduction in LACTB expression also induced tumor formation." (PMID 28642719, 2017). "That LACTB is a tumor suppressor that functions to downregulate PISD, and consequently, PE/LPE is a stunning finding that will open up new areas regarding the role of mitochondrial lipids in metabolism and proliferation." (PMID 28785375, 2017). "One proposed mechanism for LACTB-mediated tumor suppression is its involvement in apoptosis." (PMID 41223265, 2025). "Both inhibitors are predicted or validated targets of T2D-enriched miRNAs (TIMP2 by miR-93-5p; LACTB by miR-374a), suggesting that luminal-like tumor cells may be key sites of miRNA-driven repression that contributes to broader MMP activation." (PMID 40858992, 2025). "Furthermore, the influence of LACTB on mitochondrial morphology is crucial for its tumor-suppressive functions." (PMID 39941048, 2025). "Importantly, the expression and functional roles of LACTB exhibit cancer-type-specific variation, underscoring its dual function as both a tumor suppressor and an oncogene." (PMID 39941048, 2025). "In most cases, LACTB acts as a tumor suppressor, inhibiting cancer progression." (PMID 39941048, 2025). "Importantly, the reduced tumour size and increased Fe2+, PTGS2, and 4HNE levels caused by LACTB overexpression were significantly rescued by HSPA8 overexpression." (PMID 39047638, 2024). "LACTB is identified as a tumor suppressor in several tumors." (PMID 39324579, 2024). "LACTB has gained significant attention and research as a novel tumor suppressor." (PMID 38384969, 2024). "LACTB exerts its tumor suppressor function by inhibiting mitochondrial phospholipid synthesis." (PMID 38384969, 2024). "This discrepancy could stem from the diverse mechanisms through which LACTB functions in various tumor types." (PMID 38149985, 2023). "Our work provides a deeper mechanistic insight into LACTB-mediated cancer-cell death and shows the dynamics of the cellular responses a particular tumor suppressive stimulus might evoke under different genetic landscapes." (PMID 36282364, 2023). "Moreover, LACTB, a tumor suppressor gene, is downregulated in many tumor cell lines and has been found to downregulate PISD." (PMID 36716821, 2023). "Further research in this area can open new perspectives on how LACTB and the extracellular components might interact in order to inhibit tumour progression." (PMID 36282364, 2023). "While a majority of these studies support the concept that increased LACTB expression is connected with tumour suppression, some studies indicate that increased LACTB expression may instead exert a tumour promoting effect." (PMID 35626737, 2022). "In BRCA, miR-374a downregulates the protein expression of LACTB and promotes tumor metastasis." (PMID 36078157, 2022). "LACTB inhibits phosphatidylserine decarboxylase and reduces the abundance of phosphatidylethanolamine and lyso-phosphatidylethanolamine, leading to a mitochondrial state compatible with tumor suppression, decreased proliferation, and enhanced differentiation." (PMID 36078157, 2022). "In this study, a hypothesis was presented according to which the tumour suppressive effect of an increased LACTB level is mediated by a decreased activity of the mitochondrial enzyme phosphatidylserine decarboxylase (PISD)." (PMID 35626737, 2022). "A decreased availability of PE for membrane biosynthesis may become a limiting factor for cell proliferation in rapidly dividing cells, and such a mechanism would present an elegant explanatory model for the tumour suppressive effect of LACTB." (PMID 35626737, 2022). "Notably, recent studies demonstrated an emerging role of PISD in tumor regulation, where the tumor repressor LACTB downregulates PISD levels, leading to the alteration of mitochondrial lipid metabolism and differentiation of certain cancer cells." (PMID 33707636, 2021).
tumor (continued). "The mRNA expression level of LACTB was significantly increased in PAAD tumor tissue." (PMID 33507917, 2021). "Therefore, we wanted to examine whether the increased Slug levels can counteract the tumor suppressive activity of LACTB." (PMID 36375842, 2023). "Therefore, it is likely that the outcome of an increased or decreased LACTB expression in terms of tumour cell phenotype depends on a complex interplay between dysregulated metabolic enzymes and small molecule effectors, unique to each tumour type and stage of the tumorigenic process." (PMID 35626737, 2022). "Furthermore, LACTB‐mediated tumour suppression by increasing mitochondrial lipid metabolism." (PMID 33794068, 2021). "Collectively, our findings suggest LACTB to be a mediator of apoptosis-induced IMM remodeling, a possible mechanism for tumor suppression in cancer." (PMID 41223265, 2025). "Then, we induced wild type LACTB (wt‐LACTB)and LACTBM5L+R469K overexpression in different tumor cell lines, which had been reported about LACTB before." (PMID 39324579, 2024). "In this study, we demonstrated that the LACTB gene acts as an oncogene and that the mRNA expression and protein expression of LACTB are significantly higher in PAAD tumor tissue than in adjacent normal tissue." (PMID 33507917, 2021). "Our identification of a role for LACTB in mitochondrial protein release does not rule out other tumor-suppressing functions." (PMID 41223265, 2025). "Immunofluorescence in tumor tissues showed a negative correlation of Ki-67 and LACTB, indicating that LACTB is decreasing cell proliferation under in vivo conditions." (PMID 36282364, 2023). "However, in this study, the LACTB gene was recognized as an oncogene, and the mRNA expression and protein expression of LACTB were significantly higher in PAAD tumor tissue than in adjacent normal tissue." (PMID 33507917, 2021). "Although its physiological role in noncancerous cells remains unclear, LACTB is well established as a tumor suppressor in several cancer types." (PMID 41223265, 2025). "For instance, the discrepancy in LACTB expression trends between our experimental data and the GEPIA database may stem from differences between adjacent non-tumor tissue and truly healthy pancreatic tissue, highlighting the need for future validation using appropriate healthy controls." (PMID 40358702, 2025). "Conversely, LACTB silencing in non-tumorigenic breast cell lines cooperated with oncogenic drivers (HRASG12V and MYCT58A) supporting tumor formation in xenotransplants." (PMID 31430951, 2019).
cancer (21 papers, 2017 to 2025). A tumor composed of atypical neoplastic, often pleomorphic cells that invade other tissues. "Abnormal expression of LACTB in various cancers is strongly associated with cancer progression and poor postoperative prognosis." (PMID 39941048, 2025). "Altered LACTB expression and mutations are strongly linked to cancer progression and poor prognosis." (PMID 39941048, 2025). "In most cases, LACTB expression is negatively associated with cancer progression, but inconsistency exits." (PMID 36078157, 2022). "The abnormal expression of LACTB has been associated with clinicopathological features of cancer tissues and outcomes of anticancer therapies." (PMID 36078157, 2022). "Several mutations related to various types of cancers cluster at the LACTB dimer interface, including V148F, E149Q, E363K, A372T, R371K, K380N, and R382C variants." (PMID 36534696, 2022). "Given that human LACTB exerts tumor suppression activity in multiple carcinogenic cell lines, we next investigated cancer-specific missense mutations localized within LACTB." (PMID 36534696, 2022). "Reduced LACTB expression has also been shown to be associated with poor overall survival in these cancer patients, although the underlying mechanisms remain unknown." (PMID 40286848, 2025). "Aberrant LACTB expression in cancer cells is closely associated with EMT regulation." (PMID 39941048, 2025). "Furthermore, we show that expression of LACTB leads to loss of cancer stem cell properties and induction of differentiation." (PMID 36375842, 2023). "Overall, mutations in these newly evident interfaces would likely have an impact on LACTB polymerization and catalytic activity and this provides important structural context as pathogenic variants in these interfaces are linked to several cancers." (PMID 36534696, 2022). "Our structural model encompasses nearly all human cancer-associated missense mutations in LACTB and lays the foundation for characterizing additional mechanisms leading to LACTB perturbation in the regulation of lipid metabolism and mitochondrial membrane organization." (PMID 36534696, 2022). "Finally, our ability to map mutations that are identified in various cancers to the LACTB structure expands the breadth of deficiency mechanisms (beyond the down-regulation of LACTB by several miRNAs) to additionally include the impaired ability of LACTB to correctly assemble into a filament." (PMID 36534696, 2022). "The mitochondrial serine β-lactamase-like protein LACTB has emerged as a critical regulator in cancer biology, distinguished by its unique structural and functional attributes." (PMID 39941048, 2025). "Therapeutic research focused on LACTB modulation further indicates that LACTB modulation enhances drug sensitivity in both cancer cells and xenograft models." (PMID 39941048, 2025). "Through its roles in ferroptosis, autophagy, and apoptosis, LACTB demonstrates a multifaceted approach to modulating cell death in diverse cancer types." (PMID 39941048, 2025). "Modulating LACTB expression in various cancer cell types can effectively reverse these marker expressions, thereby reducing cellular migration and invasion." (PMID 39941048, 2025). "Given its role in cancer progression, treatment response, and prognosis, LACTB emerges as a promising target in precision oncology." (PMID 39941048, 2025). "Mechanistically, LACTB regulates key processes in cancer progression, including mitochondrial dynamics, epithelial–mesenchymal transition (EMT), and cell death pathways." (PMID 39941048, 2025). "In the following sections, we provide an in-depth discussion and analysis of the regulatory mechanisms controlling LACTB expression in cancer and the pathways through which it modulates cancer dynamics." (PMID 39941048, 2025).